TSPYL4 (TSPY like 4)
Synonyms: KIAA0721; dJ486I3.2
Tractability: PROTAC: ubiquitination databases record sites on it.
Gene: Protein-coding gene on chromosome 6 (116,249,964 to 116,254,075, reverse strand). Ensembl gene ENSG00000187189.
Gene Ontology:
Molecular function: protein binding
Biological process: nucleosome assembly
Cellular component: chromatin; nucleus
Genetic constraint (gnomAD): Loss-of-function variants: 8 observed, 8.53 expected, observed/expected ratio (o/e) 0.94, 90% interval 0.55 to 1.64. That is too few expected variants to judge how well the gene tolerates losing a copy. Missense variants: 344 observed, 298.15 expected, observed/expected ratio (o/e) 1.15, 90% interval 1.06 to 1.26. Synonymous variants: 124 observed, 125.14 expected, observed/expected ratio (o/e) 0.99, 90% interval 0.86 to 1.15.
Homologues: Orthologues: chimpanzee TSPYL4 (99% identical), macaque TSPYL4 (96% identical), rabbit TSPYL4 (82% identical), mouse Tspyl4 (77% identical), rat Tspyl4 (75% identical), pig TSPYL4 (67% identical), zebrafish tspy (26% identical), Drosophila melanogaster Set (19% identical), Caenorhabditis elegans spr-2 (18% identical), Drosophila melanogaster Nap1 (14% identical), zebrafish nap1l4a (12% identical), Drosophila melanogaster CG3708 (11% identical), and 2 more. Paralogues in human: TSPYL1 (56% identical), TSPYL6 (49% identical), TSPYL5 (42% identical), TSPYL2 (38% identical), TSPY4 (24% identical), TSPY10 (24% identical), TSPY3 (24% identical), TSPY8 (24% identical), TSPY9 (24% identical), TSPY1 (23% identical), TSPY2 (23% identical), SETSIP (22% identical), and 6 more.
Diseases named in the same sentence as TSPYL4 in open-access papers:
TSPYL4 is named in the same sentence as 3 diseases in open-access papers, as found by Europe PMC text mining. Sharing a sentence is not in itself a finding about the gene and the disease. The quoted sentences say what the papers report.
Dravet syndrome (1 paper, 2012). "A de novo PCDH19 missense mutation together with an inherited TSPYL4 missense variant were identified in a patient with Dravet syndrome." (PMID 22848613, 2012). "SCN1A-negative Dravet syndrome patients and patients with phenotypes resembling Dravet syndrome were checked for PCDH19 and TSPYL4 mutations." (PMID 22848613, 2012).
epilepsy (1 paper, 2012). A brain disorder characterized by episodes of abnormally increased neuronal discharge resulting in transient episodes of sensory or motor neurological dysfunction, or psychic dysfunction. "Besides, the role of TSPYL4 in epilepsy has not been reported previously." (PMID 22848613, 2012).
TSPYL4 also shares sentences with these, for which no sentence is quoted: male infertility (1 paper).